ZNF501 (zinc finger protein 501)
Description:
May be involved in transcriptional regulation. Essential for Golgi structural integrity.
Synonyms: ZNF52; MGC21738; ZNF
Tractability: PROTAC: ubiquitination databases record sites on it.
Gene: Protein-coding gene on chromosome 3 (44,729,593 to 44,737,936, forward strand). Ensembl gene ENSG00000186446.
Subcellular location: Nucleus; Nucleus, nucleolus
Subcellular location (Human Protein Atlas): Endoplasmic reticulum
Gene Ontology:
Molecular function: protein binding; sequence-specific double-stranded DNA binding; DNA-binding transcription factor activity; RNA polymerase II cis-regulatory region sequence-specific DNA binding
Biological process: Golgi organization; regulation of transcription by RNA polymerase II
Cellular component: nucleus; nucleolus
Genetic constraint (gnomAD): Loss-of-function variants: 16 observed, 17.41 expected, observed/expected ratio (o/e) 0.92, 90% interval 0.62 to 1.39. The upper end of that interval is the gene's LOEUF score, 1.39, which puts it in group 5 of 6, group 1 being the genes least tolerant of losing a copy. Missense variants: 334 observed, 320.31 expected, observed/expected ratio (o/e) 1.04, 90% interval 0.95 to 1.14. Synonymous variants: 99 observed, 101.56 expected, observed/expected ratio (o/e) 0.97, 90% interval 0.83 to 1.15.
Homologues: Orthologues: chimpanzee ZNF501 (99% identical), macaque ZNF501 (97% identical), guinea pig Znf502 (73% identical). Paralogues in human: ZNF502 (73% identical), ZNF135 (60% identical), ZNF726 (57% identical), ZNF678 (57% identical), ZNF7 (56% identical), ZNF16 (56% identical), ZNF571 (56% identical), ZNF724 (56% identical), ZNF728 (56% identical), ZNF708 (56% identical), ZNF235 (55% identical), ZNF492 (55% identical), and 164 more.
Diseases named in the same sentence as ZNF501 in open-access papers:
ZNF501 is named in the same sentence as 5 diseases in open-access papers, as found by Europe PMC text mining. Sharing a sentence is not in itself a finding about the gene and the disease. The quoted sentences say what the papers report.
depression (2 papers, 2021 to 2023). "It is possible that ZNF501/ZNF502 confer risk of depression by regulating gene expression." (PMID 34021117, 2021). "ZNF501 was found to have diminished expression with the associated variant in this study, consistent with prior ASD and depression studies." (PMID 37794117, 2023). "Seven out of 53 risk genes (B3GALTL, FADS1, TCTEX1D1, XPNPEP3, ZMAT2, ZNF501 and ZNF502) showed TWS associations with depression in two independent brain expression quantitative loci (eQTL) datasets, suggesting that these genes may represent promising candidates." (PMID 34021117, 2021).
schizophrenia (2 papers, 2021 to 2023). A major psychotic disorder characterized by abnormalities in the perception or expression of reality. "To explore if expression of ZNF501, ZNF502, B3GALTL were associated with schizophrenia and bipolar disorder, we further examined TWAS results of these three genes (i.e. ZNF501, ZNF502 and B3GALTL) in PsychENCODE24." (PMID 34021117, 2021).
psychiatric disorder (1 paper, 2023). A disorder characterized by behavioral and/or psychological abnormalities, often accompanied by physical symptoms. "We identified nine genes that have significantly different gene expression in at least one of five different psychiatric disorders compared to the control groups; one additional gene, ZNF501, was suggestive (FDR = 0.058)." (PMID 37794117, 2023).
ZNF501 also shares sentences with these, for which no sentence is quoted: autism (1 paper); bipolar disorder (1).